GUCA1B (guanylate cyclase activator 1B)
Description:
Stimulates two retinal guanylyl cyclases (GCs) GUCY2D and GUCY2F when free calcium ions concentration is low, and inhibits GUCY2D and GUCY2F when free calcium ions concentration is elevated (By similarity). This Ca(2+)-sensitive regulation of GCs is a key event in recovery of the dark state of rod photoreceptors following light exposure (By similarity). May be involved in cone photoreceptor response and recovery of response in bright light (By similarity).
Synonyms: GCAP 2; GCAP2; RP48; GCAP-2; GCAP-II; GUCA2
Tractability: Antibody: UniProt places it where antibodies can reach, with medium confidence; its Gene Ontology location is reachable by antibodies, with medium confidence.
Gene: Protein-coding gene on chromosome 6 (42,183,284 to 42,194,956, reverse strand). Ensembl gene ENSG00000112599.
Subcellular location: Cell membrane; Photoreceptor inner segment; Cell projection, cilium, photoreceptor outer segment
Subcellular location (Human Protein Atlas): Microtubules; Primary cilium; Basal body; Nuclear membrane; Nucleoplasm
Pathways (Reactome):
Sensory Perception: Inactivation, recovery and regulation of the phototransduction cascade
Gene Ontology:
Molecular function: protein binding; calcium ion binding; calcium sensitive guanylate cyclase activator activity; guanylate cyclase regulator activity
Biological process: visual perception; body fluid secretion; cell-cell signaling; cellular response to calcium ion; receptor guanylyl cyclase signaling pathway; regulation of signal transduction
Cellular component: cilium; cone photoreceptor outer segment; photoreceptor inner segment; photoreceptor disc membrane; photoreceptor outer segment membrane; plasma membrane; photoreceptor outer segment
Genetic constraint (gnomAD): Loss-of-function variants: 15 observed, 18.5 expected, observed/expected ratio (o/e) 0.81, 90% interval 0.54 to 1.25. The upper end of that interval is the gene's LOEUF score, 1.25, which puts it in group 5 of 6, group 1 being the genes least tolerant of losing a copy. Missense variants: 190 observed, 239.27 expected, observed/expected ratio (o/e) 0.79, 90% interval 0.7 to 0.9. Synonymous variants: 91 observed, 93.57 expected, observed/expected ratio (o/e) 0.97, 90% interval 0.82 to 1.16.
Homologues: Orthologues: chimpanzee GUCA1B (100% identical), dog GUCA1B (89% identical), rat Guca1b (89% identical), mouse Guca1b (88% identical), pig GUCA1B (83% identical), guinea pig GUCA1B (82% identical), rabbit GUCA1B (75% identical), zebrafish guca1b (74% identical), macaque GUCA1B (70% identical), tropical clawed frog guca1b (68% identical), Drosophila melanogaster CG7646 (32% identical), Caenorhabditis elegans ncs-2 (32% identical), and 2 more. Paralogues in human: GUCA1A (44% identical), HPCAL1 (44% identical), NCALD (43% identical), HPCA (42% identical), VSNL1 (39% identical), HPCAL4 (38% identical), NCS1 (36% identical), GUCA1C (32% identical), KCNIP1 (32% identical), KCNIP2 (30% identical), RCVRN (30% identical), KCNIP3 (29% identical), and 2 more.
Diseases named in the same sentence as GUCA1B in open-access papers:
GUCA1B is named in the same sentence as 13 diseases in open-access papers, as found by Europe PMC text mining. Sharing a sentence is not in itself a finding about the gene and the disease. The quoted sentences say what the papers report.
retinitis pigmentosa (6 papers, 2018 to 2025). Retinitis pigmentosa (RP) is an inherited retinal dystrophy leading to progressive loss of the photoreceptors and retinal pigment epithelium and resulting in blindness usually after several decades. "A mutation in GUCA1B encoding GCAP2 has been linked to retinitis pigmentosa, hG157R34." (PMID 29440717, 2018).
retinal degeneration (5 papers, 2011 to 2020). Degeneration of the retina. "In Mfrprd6 eyes, a significant 1.5- to 2.0-fold decrease was observed among transcripts of genes linked to retinal degeneration, including those involved in visual cycle (Rpe65, Lrat, Rgr), phototransduction (Pde6a, Guca1b, Rgs9), and photoreceptor disc morphogenesis (Rpgrip1 and Fscn2)." (PMID 25357075, 2014).
retinal dystrophies (4 papers, 2014 to 2023). "In terms of retinal dystrophies, the molecular spectrum of GUCA1B has been evaluated, and several variants have been identified, although none of them have been classified as disease-causing." (PMID 37761846, 2023).
autosomal dominant retinitis pigmentosa (2 papers, 2013 to 2018). Autosomal dominant retinitis pigmentosa (RP) is an autosomally dominant inherited retinal dystrophy leading to progressive loss of the photoreceptors and retinal pigment epithelium and resulting in blindness usually after several decades. "One mutation has been described in the GUCA1B gene encoding GCAP2, that has been linked to autosomal dominant retinitis pigmentosa: hG157R34." (PMID 29440717, 2018).
retinoblastoma (1 paper, 2023). A malignant tumor that originates in the nuclear layer of the retina. "Subtype 1 retinoblastoma likely arise from cone as it usually has a higher expression of cone markers and Photoreceptor genes (such as ARR3 and GUCA1B)." (PMID 37777551, 2023).
GUCA1B also shares sentences with these, for which no sentence is quoted: Blindness (2 papers); cone dystrophy (2); cone-rod dystrophies (2); retinal disease (2); AIDS (1); Parkinson's (1); spinocerebellar ataxia (1); viral infection (1).